TRBV7-9 (T cell receptor beta variable 7-9)
Description:
V region of the variable domain of T cell receptor (TR) beta chain that participates in the antigen recognition. Alpha-beta T cell receptors are antigen specific receptors which are essential to the immune response and are present on the cell surface of T lymphocytes. Recognize peptide-major histocompatibility (MH) (pMH) complexes that are displayed by antigen presenting cells (APC), a prerequisite for efficient T cell adaptive immunity against pathogens. Binding of alpha-beta TR to pMH complex initiates TR-CD3 clustering on the cell surface and intracellular activation of LCK that phosphorylates the ITAM motifs of CD3G, CD3D, CD3E and CD247 enabling the recruitment of ZAP70. In turn ZAP70 phosphorylates LAT, which recruits numerous signaling molecules to form the LAT signalosome. The LAT signalosome propagates signal branching to three major signaling pathways, the calcium, the mitogen-activated protein kinase (MAPK) kinase and the nuclear factor NF-kappa-B (NF-kB) pathways, leading to the mobilization of transcription factors that are critical for gene expression and essential for T cell growth and differentiation. The T cell repertoire is generated in the thymus, by V-(D)-J rearrangement. This repertoire is then shaped by intrathymic selection events to generate a peripheral T cell pool of self-MH restricted, non-autoaggressive T cells. Post-thymic interaction of alpha-beta TR with the pMH complexes shapes TR structural and functional avidity.
Synonyms: TRBV79; TCRBV6S4A1; TCRBV7S9; TCRB
Tractability: Antibody: a drug acting on it is in phase 2 or 3 trials; its Gene Ontology location is reachable by antibodies, with high confidence; UniProt places it where antibodies can reach, with medium confidence; UniProt predicts a signal peptide or a membrane-spanning region.
Gene: T-cell receptor variable (V) gene on chromosome 7 (142,529,290 to 142,529,762, forward strand). Ensembl gene ENSG00000278030.
Subcellular location: Cell membrane
Pathways (Reactome):
Immune System: Co-inhibition by PD-1; Downstream TCR signaling; Generation of second messenger molecules; Immunoregulatory interactions between a Lymphoid and a non-Lymphoid cell; Phosphorylation of CD3 and TCR zeta chains; Translocation of ZAP-70 to Immunological synapse
Gene Ontology:
Molecular function: MHC protein binding; peptide antigen binding
Biological process: cell surface receptor signaling pathway; immune response
Cellular component: plasma membrane
Homologues: Orthologues: chimpanzee BV7-9 (97% identical), macaque TRBV7-9 (83% identical). Paralogues in human: TRBV7-7 (75% identical), TRBV7-6 (74% identical), TRBV7-3 (68% identical), TRBV7-4 (68% identical), TRBV7-2 (67% identical), TRBV11-1 (65% identical), TRBV7-1 (64% identical), TRBV11-2 (60% identical), TRBV11-3 (60% identical), TRBV12-4 (55% identical), TRBV12-5 (55% identical), TRBV12-3 (54% identical), and 39 more.
Diseases named in the same sentence as TRBV7-9 in open-access papers:
TRBV7-9 is named in the same sentence as 3 diseases in open-access papers, as found by Europe PMC text mining. Sharing a sentence is not in itself a finding about the gene and the disease. The quoted sentences say what the papers report.
tumor (1 paper, 2013). "Here we present data showing that the molecular basis for at least part of the anti-tumor activity by ABR-217620 resides in the distinct interaction between the T lymphocyte membrane protein TRBV7-9 and the Sag SEA/E-120 in the fusion protein bound to the 5T4 antigen on tumor cells." (PMID 24194959, 2013).
TRBV7-9 also shares sentences with these, for which no sentence is quoted: breast carcinoma (1 paper); COVID-19 (1).